EPCAM (epithelial cell adhesion molecule)
Diseases named in the same sentence as EPCAM in open-access papers (continued):
Sharing a sentence is not in itself a finding about the gene and the disease.
tumor (continued). "Further, miR-181 and miR-130 are overexpressed in EpCAM+ cells than in EpCAM cells and cause stemness features in EpCAM+ tumor cells." (PMID 35986321, 2022). "The tumor-suppressive role of Smurf2 was found to be associated with cell migration and EpCAM expression; hence, Smurf2 can be considered a positive biomarker of cancer stem cell-like properties." (PMID 35361871, 2022). "Univariate analysis showed a positive significant association between tumor size, tumor stage, tumor differentiation, vascular, neural, and lymph node invasion and higher expression of EpCAM." (PMID 35016698, 2022). "The CellSearch system (Menarini Silicon Biosystems) uses magnetic beads that are biofunctionalized against epitopes of tumor‐associated EpCAM (Epithelial cell adhesion molecule) to enrich CTCs from patient blood." (PMID 35573135, 2022). "The tumor-suppressive role of Smurf2 was found to be associated with cell migration and EpCAM expression, which is associated with stem cell-like properties of cancer cells." (PMID 35361871, 2022). "Increasing evidence suggests that EPCAM is one of the most highly immunogenic tumor-associated antigens." (PMID 36131343, 2022). "In exploratory univariate analysis, we found three markers associated with OS in the tumor compartment (EpCAM, P = 0.0013; Ki‐67, P = 0.034; STING, P = 0.036) and three in the stromal compartment (CD8, P = 0.028; CD25, P = 0.013; CD127, P = 0.0059)." (PMID 34018684, 2022). "Tumor disease development is associated with alternations, which can change the expression of epithelial markers, such as EpCAM." (PMID 35054482, 2022). "High expression levels of Galectin 3 and EpCAM are associated with poor patient survival rates and a higher metastatic disease burden in all tumor types of this study." (PMID 35337112, 2022). "EpCAM, as a common highly expressed molecule in cancer cells, is taken as a tumor-associated antigen." (PMID 36369033, 2022). "A similar situation has also been reported for the tumor–associated antigen EpCAM, which promotes Th2 cell–mediated immune escape." (PMID 36388191, 2022). "EpCAM and c-Met are not only considered two prominent tumor-associated antigens but also expressed on healthy tissues." (PMID 35986321, 2022). "EPCAM is a transmembrane glycoprotein that is consistently expressed by epithelial-derived tumor cells and is associated with poor clinical outcome." (PMID 35101049, 2022). "Our data also confirm that CEA and EpCAM expression is significantly higher in tumor tissue of the diagnostic biopsy compared with the corresponding resected pCR tumor bed." (PMID 33799475, 2021). "The invasive tumor cells tend to lose their epithelial antigens by the epithelial to mesenchymal transition process, which results in loss of EpCAM on CTCs and made the capturing of CTCs more difficult." (PMID 34112129, 2021). "The location of this non-synonymous polymorphism in the thyroglobulin (TY) domain of the EPCAM gene suggests its role in inhibiting cathepsins, a family of cysteine proteases that are frequently secreted by tumour cells during metastasis." (PMID 34573430, 2021). "In BsAb therapy, while one antibody activates the effector T cell receptors such as CD3 and CD28, the other antibody causes a tumor-associated antigen, such as AFP, GPC3, and EpCAM, to initiate tumor cytotoxicity." (PMID 34696292, 2021). "In patients undergoing LT, LR, transarterial chemoembolization (TACE), or radiotherapy for HCC, EpCAM+ CTC count at baseline has been associated with increased tumor recurrence, shorter overall survival, and shorter progression-free survival." (PMID 34884878, 2021). "Other groups also used OVs encoding CD3-BsAbs targeting EpCAM, Eph-A2 and CD44v6 and observed anti-tumor activities against several tumor models." (PMID 33466732, 2021).
tumor (continued). "Both EphA2 and EpCAM are tumor-associated antigens that are overexpressed in patients with esophageal squamous cell carcinoma but are not tumor-specific antigens." (PMID 34386424, 2021). "In this regard, CAR-T cells targeting epithelial cell adhesion molecule (EpCAM), a tumor-associated antigen overtly presented on the cell surface of various carcinomas, is a typical precedent." (PMID 34475869, 2021). "Of interest, an elevated count of large EpCAM positive tumor cell fragments in the blood of PCa patients is associated with poor patient outcomes and, large EVs, termed oncosomes, released by PCa cells are associated with advanced disease." (PMID 33589770, 2021). "EpCAM is a smart target for ascites, since it is expressed on tumour cells causing peritoneal carcinomatosis, while other cells of peritoneum lack EpCAM expression." (PMID 34577584, 2021). "DANCR silencing in HCC cells downregulates the expression of several stemness-associated genes, including CD133, CD90, and EpCAM, and decreases the number and dimension of tumor spheroids." (PMID 34572776, 2021). "Former studies reported significant association of EpCAM expression in HCC with high tumor grade and AFP level." (PMID 35070966, 2021). "The previous studies demonstrated that EPCAM overexpression was an independent unfavorable prognostic factor and was linked with larger tumor size and lymph node metastasis in GC patients." (PMID 34113647, 2021). "CEA and EpCAM expressions were significantly higher in the diagnostic biopsy compared with the corresponding tumor bed (p < 0.01)." (PMID 33799475, 2021). "Loss of EpCAM coincided with increased expression of mesenchymal marker vimentin in primary human tumors and in disseminated tumor cells." (PMID 32507912, 2020). "Targeting different tumor-associated antigens (EpCAM/EGFR) on the tumor cell is expected to support the combinatorial approach by avoiding competition between the fusion proteins mediating the first and the costimulatory signal, respectively." (PMID 32504247, 2020). "High EpCAM expression is associated with proliferation, while EpCAMlow/negative expression is correlated with migration, invasion and tumor cell dissemination." (PMID 32764280, 2020). "As EpCAM is highly expressed on the surface of many cancer cells and has been associated with tumor cell proliferation, migration and invasion, some targeted therapies have been developed against this protein." (PMID 32764280, 2020). "Overexpression of epithelial cell adhesion molecule (EpCAM) has been associated with chemotherapeutic resistance, leads to aggressive tumor behavior, and results in an adverse clinical outcome." (PMID 32814771, 2020). "EpCAM has, moreover, been associated with the initiation of diverse tumor types, and also with disease recurrence and poor clinical outcomes." (PMID 33276608, 2020). "In this study, we introduce a dual-target system focusing on the tumor-associated antigens EpCAM and EGFR." (PMID 32504247, 2020). "The association between metastasis and tumor hypoxia is believed to be mediated by changes in the expression of cell adhesion molecules, such as EpCAM (epithelial cell adhesion molecule) and cadherins, which are critical for cell adhesion." (PMID 32292512, 2020). "In our series, CRC was the most informative tumor, being the unique neoplasm that showed a complete loss of EPCAM expression, identifying patients with EPCAM 3′-end deletions with 100% specificity and confirming our previous results." (PMID 33003511, 2020). "EpCAM has been studied in a wide-variety of human carcinomas and normal epithelial tissues and it is considered to be the most studied tumour-associated antigen." (PMID 32046162, 2020).
tumor (continued). "Although neoplasms from patients #12 and #13 shared the same pathogenic variant, they showed different EPCAM expressions." (PMID 33003511, 2020). "Increased EpCAM expression in patient tumour samples is associated with poor prognosis and therapeutic irresponsiveness." (PMID 32046162, 2020). "The epithelial cell adhesion molecule (EpCAM) is a tumor-associated antigen and a potential target for tumor vaccine." (PMID 33143243, 2020). "EpCAM is one of the first identified human tumor-associated biomarkers and is now considered to be a marker of tumor-initiating cells." (PMID 33154781, 2020). "Elevated EpCAM levels are associated with increased cell proliferation, tumor development and progression, as well as with reduced overall survival of cancer patients." (PMID 32226524, 2020). "The transmembrane glycoprotein human epithelial cell adhesion molecule (EpCAM) is a one of the most frequently and intensely expressed tumor-associated antigens in a number of malignancies." (PMID 33322601, 2020). "At first, increased EpCAM expressions were found in almost all carcinomas and known to associated with tumor grading, staging, and prognosis." (PMID 33014844, 2020). "Proteins such as CD9, CD63, and CD81 are located on the exosome surface, and tumor-associated markers (HER2, EpCAM) are also present on tumor-associated exosomes." (PMID 32582658, 2020). "As many studies suggest that soluble EpCAM is associated with an aggressive tumor phenotype, soluble EpCAM was also considered to be a marker for CCA recurrence." (PMID 32039729, 2020). "High expression of EpCAM in OC is associated with tumor recurrence, chemoresistance and poor patient prognosis." (PMID 32257947, 2020). "Since only homogeneous EpCAM-expression was associated with more aggressive tumor behaviour and subsequently, a poorer outcome, we were interested in the predictive value of a single biopsy towards the overall EpCAM-score (E+/+, E+/−, or E−/−)." (PMID 33225916, 2020). "Positive CTC selection is carried out using tumor-associated cell surface antigens, generally EpCAM and cytokeratins (CK8, CK18, and CK19)." (PMID 37361495, 2020). "EpCAM appears to increase the invasiveness potential of tumor cells as well as the risk of portal vein invasion." (PMID 31781608, 2019). "EpCAM in PCa is associated with tumor progression and metastasis and therapeutic resistance via the PI3K/Akt/mTOR signaling pathway." (PMID 31324239, 2019). "In liver and pancreatic cancer, a high expression of EpCAM is associated with the dedifferentiation of tumor cells that have regained stem cell-like features." (PMID 31709180, 2019). "The NP-TRFIA assay was evaluated for its efficacy in the identification of known tumor-associated proteins (EpCAM and ITGA3) on the surface of EVs." (PMID 31296879, 2019). "It was found that changes in the expression of epithelial (CKs and EpCAM) and mesenchymal markers were caused by changing the growth type of the tumor population." (PMID 30930631, 2019). "Expression of some liver CSC markers such as CD133 and EpCAM has been reported to be associated with tumor angiogenesis, low response rates to chemotherapy, and poor overall prognoses in patients with HCC." (PMID 30326936, 2018). "We demonstrate for the first time that EpCAM is involved in tumour growth, chemo−/radiotherapy response and associated with activation of the PI3K/Akt/mTOR signalling pathway in CaP animal models in vivo." (PMID 30419852, 2018). "From our data we conclude that an ACF-induced increase in EpCAM expression reflects the selection of a CSC subpopulation that underlies tumor development and drug resistance in EAC." (PMID 30116994, 2018).
tumor (continued). "Small islands of tumor cells separated from the major tumor area frequently showed loss of EpCAM expression at the edges, which was linked to gain of vimentin expression, itself suggestive of partial EMT within tumors." (PMID 30275505, 2018). "EGFR/EpCAM subgroups of patients were tested for associations with the clinical parameters tumor localization, grading, T stage, N stage, age, and p16 status, which is a surrogate marker for HPV infection." (PMID 30261040, 2018). "It is well known that EpCAM is more widely expressed on CSCs, and it is also regarded as a tumor-associated antigen (TAA)." (PMID 28290053, 2018). "In our study, we found that expression of EpCAM is associated with tumour responsiveness to DTX treatment in vivo." (PMID 30419852, 2018). "In their studies, opsonization with catumaxomab caused the activation of PBMCs and destroyed EpCAM-positive tumor cells." (PMID 28931402, 2017). "Dt81Hepa1-6 cells are characterized by the presence of a large population of EpCAM+ cells, a hallmark of tumor inducing cells." (PMID 28152020, 2017). "For example, while we have exemplified the technology here using a BiTE that recognises a carcinoma‐associated antigen (EpCAM), it is also possible to use the BiTE approach to target cytotoxicity to tumour‐associated fibroblasts or other stromal cells." (PMID 28634161, 2017). "EpICD, as the intracellular domain of EpCAM, is associated with the Wnt pathway which regulates gene transcription when translocated into the nucleus resulting in cell proliferation and tumor formation." (PMID 28931402, 2017). "In this scenario, tumor cells with activated EpCAM i.e. the released EpICD associates with FHL2, β-catenin which form a nuclear complex with Lef-1 and induces transcription of genes associated with cell proliferation." (PMID 28903370, 2017). "Expression of EpCAM by tumor cells is associated with increased tumorigenicity and anchorage-independent growth." (PMID 28152020, 2017). "A second study, representative of a Chinese HCC cohort (90% hepatitis B-associated HCC), revealed a predictive power of EpCAM-positive CTC for tumor recurrence after liver resection." (PMID 29163804, 2017). "Co-expression of membranous EpCAM and nuclear β-catenin in the tumor specimens in our study population was associated with an AFP level < 1200 ng/mL after SIOPEL neoadjuvant chemotherapy, indicating improved chemosensitivity." (PMID 28851352, 2017). "Epithelial cell adhesion molecule (EpCAM) is a tumor‐associated cell adhesion molecule with oncogenic potential in many endothelium‐derived cancers." (PMID 28781954, 2017). "Major responses have been demonstrated in various B‐cell malignancies, and BiTEs have been designed targeting different tumour‐associated antigens including EpCAM, Her2/neu, EGFR, CEA, EphA2, CD33 and MCSP with some currently under clinical evaluation." (PMID 28634161, 2017). "Correlating PD-L1 abundance with flow-cytometric data obtained from EpCAM depleted EOC tumor tissue cells allows a better understanding of associated local immunological players." (PMID 28266500, 2017). "Treatment with either drug caused significant tumor shrinkage in comparison with the control group; however, substantial enrichment of the EpCAM-positive cells was observed." (PMID 28574829, 2017). "The free and virally encoded EpCAM BiTE also induced significant T‐cell activation of tumour‐associated lymphocytes (assessed by CD25 expression) in all patients' samples, even within the likely immune‐tolerising environment of the malignant exudate fluid." (PMID 28634161, 2017). "In particular, EpCAM membrane staining in this type of cells also distinguished carcinoma cells from tumour-associated macrophages." (PMID 28846747, 2017). "Patients with at least one tumor-associated transcript found in their CTCs, enriched from peripheral blood using immunomagnetic EpCAM and mucin 1 detection, had a PFS of 66.0 vs. 138.0 days in those who did not." (PMID 28626429, 2017).
tumor (continued). "EpCAM is a cell surface glycoprotein that mediates cell-cell adhesion in epithelial tissues; diminished EpCAM expression is linked to tumor invasiveness and progression in CRC." (PMID 28030836, 2017). "Consistent with this, increased expression of EPCAM in NPC tumours was associated with more advanced stage of the disease." (PMID 28959019, 2017). "Histologically, foci exhibiting EPCAM loss in EPCAM-PL tumors were dominantly distributed in poorly differentiated tumor components and/or in the invasive tumor front." (PMID 26528695, 2016). "EpCAM up-regulation is associated with cancer progression and EpCAM is found on circulating tumour cells and metastases." (PMID 27842504, 2016). "According to our data, EPCAM-PL was associated with an invasive front, poor differentiation, signet ring cell histology, tumor budding, lymphovascular/perineural invasion, nodal/distant metastasis, CIMP-high, and poor DFS in CRC." (PMID 26528695, 2016). "EPCAM-loss foci were more frequently observed in the invasive front (84%) than in the tumor center (74%) and superficial tumor (32%) areas." (PMID 26528695, 2016). "In aCP, a strong EpCAM expression has been associated with a higher long-term risk of tumour regrowth." (PMID 27431859, 2016). "Selective delivery with an aptamer targeting the tumor-associated antigen EpCAM, that is highly expressed in epithelial cancers and their tumor-initiating cells (TIC), has been recently developed as a flexible platform for targeted therapy." (PMID 27827876, 2016). "Although all three entities are thought to be derived from the same cell of origin, and aCP and pCP are described as representing variants of the same tumour class, both EpCAM protein and gene expression levels revealed clear differences." (PMID 27431859, 2016). "Our finding showed that BRCA1 knockdown induced the expansion of the CD49f+EpCAM+ subpopulation in the CD44+CD24– cell subset of MCF10DCIS tumor cells, confirming the relationship between BRCA1 deficiency and luminal progenitors." (PMID 27556296, 2016). "In a very aggressive triple-negative breast cancer xenograft model, the EpCAM-AsiC treatment caused complete tumor regression." (PMID 27827876, 2016). "Another finding was that the partial loss of EPCAM expression can frequently be observed in tumor budding at the invasive margin of CRCs." (PMID 26528695, 2016). "In all three types of tumour entities, the presence of tumour was associated with an increase of circulating EpCAM+ and EpCAM+CD147+ taMPs." (PMID 27127176, 2016). "EpCAM+CD147+ taMPs were associated with a slightly higher overall positive predictive values for the investigated tumour entities: 80.36% (PPV) and 83.87% (NPV), respectively, with an overall sensitivity of 94.74% and specificity of 54.17%." (PMID 27127176, 2016). "In IHC, Oct4, CD133 and EpCAM were independently related to tumor progression, while Sox2 were associated with well or moderate differentiation (all p<0.05)." (PMID 27557490, 2016). "EpCAM high expression was significantly associated with old age (p=0.011), greater curvature and anterior wall of stomach (p=0.034), larger tumor size (p=0.036)." (PMID 27557490, 2016). "E-cadherin is an epithelial cell adhesion molecule and loss of its expression prominently associates with tumor invasiveness, metastatic dissemination and poor patient prognosis." (PMID 27057626, 2016). "Due to the limitation of EpCAM-based capture assays for the detection of various circulating tumor associated cells, many other technologies have been developed including size-execution enrichment devices." (PMID 27706044, 2016). "Histologically, the EPCAM-loss foci in the metastatic lesions were primarily distributed in poorly differentiated tumor clusters." (PMID 26528695, 2016). "Consistent with previous studies, EpCAM expression was significantly associated with tumor stage and tumor grade." (PMID 26356670, 2015).